STAMBP (STAM binding protein)
Description:
Zinc metalloprotease that specifically cleaves 'Lys-63'-linked polyubiquitin chains. Does not cleave 'Lys-48'-linked polyubiquitin chains. Plays a role in signal transduction for cell growth and MYC induction mediated by IL-2 and GM-CSF. Potentiates BMP (bone morphogenetic protein) signaling by antagonizing the inhibitory action of SMAD6 and SMAD7. Has a key role in regulation of cell surface receptor-mediated endocytosis and ubiquitin-dependent sorting of receptors to lysosomes. Endosomal localization of STAMBP is required for efficient EGFR degradation but not for its internalization. Involved in the negative regulation of PI3K-AKT-mTOR and RAS-MAP signaling pathways.
Synonyms: AMSH; MICCAP
Tractability: Small molecule: a high-quality ligand is known; it has a binding pocket of medium quality. Antibody: UniProt places it where antibodies can reach, with high confidence; its Gene Ontology location is reachable by antibodies, with high confidence; the Human Protein Atlas places it where antibodies can reach. PROTAC: UniProt records ubiquitination sites on it; ubiquitination databases record sites on it; its protein half-life has been measured; a small molecule that binds it is known.
Target class: Enzyme; Hydrolase
Gene: Protein-coding gene on chromosome 2 (73,828,916 to 73,873,659, forward strand). Ensembl gene ENSG00000124356.
Subcellular location: Nucleus; Membrane; Cytoplasm; Early endosome
Subcellular location (Human Protein Atlas): Nucleoplasm; Cytosol; Plasma membrane
Pathways (Reactome):
Metabolism of proteins: Metalloprotease DUBs
Gene Ontology:
Molecular function: deubiquitinase activity; K63-linked deubiquitinase activity; protein binding; protein domain specific binding; metal-dependent deubiquitinase activity; metallopeptidase activity; peptidase activity
Biological process: mitotic cytokinesis; negative regulation of phosphatidylinositol 3-kinase/protein kinase B signal transduction; negative regulation of Ras protein signal transduction; protein deubiquitination; cell surface receptor signaling pathway via JAK-STAT; positive regulation of cell population proliferation; protein K63-linked deubiquitination
Cellular component: cleavage furrow; cytoplasm; cytosol; early endosome; extracellular exosome; membrane; nucleoplasm; nucleus; plasma membrane; endosome
Genetic constraint (gnomAD): Loss-of-function variants: 29 observed, 47.72 expected, observed/expected ratio (o/e) 0.61, 90% interval 0.45 to 0.83. The upper end of that interval is the gene's LOEUF score, 0.83, which puts it in group 3 of 6, group 1 being the genes least tolerant of losing a copy. Missense variants: 461 observed, 538.57 expected, observed/expected ratio (o/e) 0.86, 90% interval 0.79 to 0.93. Synonymous variants: 210 observed, 201.11 expected, observed/expected ratio (o/e) 1.04, 90% interval 0.93 to 1.17.
Homologues: Orthologues: chimpanzee STAMBP (99% identical), macaque STAMBP (96% identical), rabbit STAMBP (96% identical), guinea pig STAMBP (95% identical), dog STAMBP (95% identical), pig STAMBP (92% identical), rat Stambp (84% identical), mouse Stambp (83% identical), tropical clawed frog stambp (69% identical), zebrafish stambpa (63% identical), zebrafish stambpb (59% identical), Drosophila melanogaster CG2224 (41% identical). Paralogues in human: STAMBPL1 (56% identical).
Diseases named in the same sentence as STAMBP in open-access papers:
STAMBP is named in the same sentence as 49 diseases in open-access papers, as found by Europe PMC text mining. Sharing a sentence is not in itself a finding about the gene and the disease. The quoted sentences say what the papers report.
microcephaly (7 papers, 2016 to 2022). A congenital or acquired developmental disorder in which the circumference of the head is smaller than normal for the person's age and sex. "Most patients with STAMBP mutations have shown global developmental delay, microcephaly, capillary malformation, epilepsy, and dysmorphic features." (PMID 36033615, 2022). "Whole-exome sequencing revealed that the microcephaly-capillary malformation syndrome was related to recessive mutations in STAMBP." (PMID 31795200, 2019). "STAM-binding protein (STAMBP) is a zinc metalloprotease involved in cell cycle regulation recently linked to the neuronal loss underlying microcephaly-capillary malformation syndrome." (PMID 27293953, 2016). "Interestingly, we found several differentially expressed genes following infection with ZIKV Uganda, including COL4A1, MIR17HG, TUBA1A, SLC2A1 and STAMBP, which are associated with microcephaly according to the comparative toxicogenomics database." (PMID 33121145, 2020). "Mutations in the STAMBP gene, which encodes a deubiquitinating isopeptidase called STAM-binding protein, are related to global developmental delay, microcephaly, and capillary malformation." (PMID 36033615, 2022). "Cortical organoids with STAMBP knockout (KO) showed significantly lower proliferation of neural stem cells (NSCs), leading to smaller organoids that are characteristic of microcephaly." (PMID 36033615, 2022).
breast carcinoma (6 papers, 2020 to 2025). "Increasing evidence has shown that STAMBP is highly elevated and is linked to poor clinical prognosis in multiple cancers, such as lung adenocarcinoma, breast cancer, triple-negative breast cancer, and PC." (PMID 39242557, 2024). "qRT-PCR analysis revealed higher STAMBP mRNA levels in tumor tissues compared to adjacent normal tissues from 15 patients with ERα-positive breast cancer." (PMID 41301420, 2025). "To investigate STAMBP’s functional roles in breast cancer, we conducted GO and KEGG pathway enrichment analyses using TCGA data, identifying key biological processes and signaling pathways linked to STAMBP expression." (PMID 41301420, 2025). "This study investigates STAMBP’s role in breast cancer progression and evaluates its potential as a therapeutic target." (PMID 41301420, 2025). "Specifically, in breast cancer, STAMBP knockdown inhibited cell mobility and invasion by compromising EGFR/MAPK signaling pathway activation and inducing the degradation of actin-binding proteins." (PMID 38594742, 2024). "STAMBP overexpression promotes the malignant behavior of cancer cells in multiple cancers, such as breast cancer, triple-negative breast cancer, PC, and lung cancer." (PMID 39242557, 2024). "In addition, compared with that in normal tissue, the level of STAMBP mRNA in breast cancer tissues in patients with Stage 1, 2, 3, or 4 breast cancer was increased." (PMID 36434041, 2022). "Recent studies have shown that the deubiquitinase STAMBP suppresses the ubiquitination of RAI14 and stabilizes its protein level, thereby promoting breast cancer progression." (PMID 39160347, 2024). "Western blot assays confirmed STAMBP expression in tumor and paired adjacent non-tumor (para-tumor) tissues from 12 patients with ERα-positive breast cancer." (PMID 41301420, 2025). "Moreover, compared with that in normal tissues, the level of STAMBP mRNA in breast cancer tissues of breast cancer patients with or without lymph node metastasis was increased." (PMID 36434041, 2022).
melanoma (4 papers, 2019 to 2024). A malignant, usually aggressive tumor composed of atypical, neoplastic melanocytes. "For example, STAMBP potentiates the metastatic potential of melanoma cells by modulating SLUG stability." (PMID 39242557, 2024). "A recent study showed that STAMBP expression contributes to melanoma cell migration and invasion through the stabilization of SLUG expression." (PMID 31795200, 2019). "Upregulation of miR-378a-5p in M14 melanoma cells reduced both mRNA and protein levels of STAMBP, SP1, KLF9, FUS-1, and SUFU when compared with control transfected cells, while miR-378a-5p inhibition led to an opposite effect, upregulating the expression of target genes." (PMID 32060259, 2020).
lung adenocarcinoma (3 papers, 2021 to 2024). A carcinoma that arises from the lung and is characterized by the presence of malignant glandular epithelial cells. "Although STAMBP has been implicated in the tumor metastasis of lung adenocarcinoma and melanoma, the pathological role of STAMBP in TNBC has not been elucidated." (PMID 36434041, 2022).
pancreatic cancer (3 papers, 2024 to 2025). "Elevated STAMBP in pancreatic cancer has been found to interact with E2F1, preventing its degradation and promoting the PDK1-mediated Warburg effect, which contributes to chemotherapy resistance." (PMID 40149859, 2025). "STAMBP’s role in promoting malignancy in pancreatic cancer cells and its involvement in the regulatory mechanism of hsa_circ_0007334 has also been reported." (PMID 38742115, 2024). "Specifically, STAMBP is overexpressed in the pancreatic tumors as compared to the normal organ in a grade-dependent manner and is also significantly associated with poor overall and disease-free survival of PC patients." (PMID 39242557, 2024). "However, it remains unclear whether entrectinib can simultaneously inhibit both tyrosine kinase and the STAMBP protein to further enhance the sensitivity of pancreatic cancer to gemcitabine, which warrants further exploration in the future." (PMID 39242557, 2024).
esophageal squamous cell carcinoma (2 papers, 2023 to 2025). Esophageal squamous cell carcinoma (ESCC) is a type of esophageal carcinoma (EC) that can affect any part of the esophagus, but is usually located in the upper or middle third. "STAMBP is a deubiquitinating protein which has been identified as a potential diagnostic biomarker for early Alzheimer’s disease, fibromyalgia and squamous cell carcinoma of the esophagus." (PMID 39962379, 2025). "Such as STAMBP, ST1A1 was also associated with an increased risk of esophageal squamous cell carcinoma in prior investigations." (PMID 39962379, 2025).
fibromyalgia (2 papers, 2022 to 2023). A chronic disorder of unknown etiology characterized by pain, stiffness, and tenderness in the muscles of neck, shoulders, back, hips, arms, and legs. "The top five proteins that distinguished fibromyalgia patients from plasma controls were in serum STAMBP, SIRT2, CD40, AXIN1 and IL-7 and in CSF (CCL19, CCL23, IL-18, CX3CL1, FGF19, CXCL10, CCL11)." (PMID 36327322, 2022).
acute coronary syndrome (1 paper, 2025). Signs and symptoms related to acute ischemia of the myocardium secondary to coronary artery disease. "While detection of higher levels of STAMBP in sweat shows potential for individual markers, further research is needed to determine whether sweat can provide complementary or unique information compared to traditional plasma biomarkers in the context of acute coronary syndromes." (PMID 39955425, 2025).
breast tumor (1 paper, 2022). "Compared with normal tissues, the expression of STAMBP was significantly higher in human breast tumor tissues, especially in human TNBC tissues." (PMID 36434041, 2022).
dementia (1 paper, 2019). Loss of intellectual abilities interfering with an individual's social and occupational functions. "Our study highlights the changes and potential contributions of several chemokines (CXCL1, CCL3, CXCL5, CXCL6, CCL3, CCL19), interleukins (IL8, IL6-RA, IL18-BP), and other immune markers (OSM, ALCAM, OPG, CHIT1, YKL-40, STAMBP, MMP-9, MMP-10) in the prodromal and dementia phases of AD." (PMID 31694701, 2019).
HIV-1 infection (1 paper, 2020). The type species of lentivirus and the etiologic agent of acquired immunodeficiency syndrome (AIDS). "Random forest analysis was performed to pin-point proteins discriminating between groups; five proteins (STAMBP, CD5, TFG-α, TRANCE, AXIN1) were the strongest prediction factors for treated HIV-1 infection." (PMID 32906648, 2020).
influenza (1 paper, 2025). An acute viral infection of the respiratory tract, occurring in isolated cases, in epidemics, or in pandemics; it is caused by serologically different strains of viruses (influenzaviruses) designated A, B, and C, has a 3-day incubation period, and usually lasts for 3 to 10 days. "While both BCG and influenza vaccination were associated with lower relative concentrations of circulating inflammatory markers in men, it is important to recognise that the proteome profiles differ for the two vaccines, with some notable overlap (e.g. STAMBP and TNFSF14)." (PMID 40949320, 2025).
male infertility (1 paper, 2022). The inability of the male to effect fertilization of an ovum after a specified period of unprotected intercourse. "Among the other validated hits were proteins involved in the ubiquitin proteasome system (STAMBP and MYLIP), transcription (MTA1, PKNOX2), translation (EIF4E3), male infertility (RABL2A, DAZAP1), and virus-induced oncogenesis (MTA1)." (PMID 35452674, 2022).
metastatic cancer (1 paper, 2022). A carcinoma which has spread from the original site of growth to another anatomic site. "Further understanding of STAMBP-dependent RAI14 protein stability may guide the development of improved strategies for the treatment of metastatic cancer, including TNBC." (PMID 36434041, 2022).
metastatic tumors (1 paper, 2021). "The volume of the tumors in the lung was smaller and the number of metastatic tumors in the chest wall was lower in the STAMBP knockdown group." (PMID 34102455, 2021). "However, only 6 out of 11 nude mice from the STAMBP knockdown group developed a tumor on the left lung and 3 out of 6 mice formed metastatic tumors in the chest wall." (PMID 34102455, 2021). "Importantly, the expression of STAMBP, EGFR in cell membrane and phosphorylated ERK in cell nucleus was markedly reduced in the STAMBP knockdown tumor tissues from the lung and metastatic tumors from the chest wall." (PMID 34102455, 2021).
neuroendocrine tumors (1 paper, 2020). "We propose that compounds that modulate the deubiquitinase activity of either USP33 or STAMBP may be of therapeutic use in the treatment of neuroendocrine tumors that result from impaired GCGR trafficking and signaling." (PMID 32967969, 2020).
spinal diseases (1 paper, 2024). "Other than causing inflammation, not much is known about the function of STAMBP in spinal diseases and bone homeostasis regulation." (PMID 38895179, 2024).
spondylolisthesis (1 paper, 2024). A condition in which there is forward displacement of a vertebral bone over the on below it. "Spondylolisthesis/spondylolysis also had no causal effect on the levels of STAMBP (p = 0.5197), CD6 isoform (p = 0.7240), MCP2 (p = 0.5843), and LAP‐TGF‐β1 (p = 0.0879)." (PMID 38895179, 2024).
Stroke (1 paper, 2023). Sudden impairment of blood flow to a part of the brain due to occlusion or rupture of an artery to the brain. "STAMBP is a negative regulator of the NALP7 and NLRP3 inflammasomes, the latter of which has been identified as a potential therapeutic target to reduce pro-inflammatory stress after stroke." (PMID 37794467, 2023). "Twenty proteins were associated with outcome in univariable models after correction for multiple testing (FDR < 0.05), and for 5 the association was independent of clinical variables, including stroke severity (TNFSF14 [LIGHT], OSM, SIRT2, STAMBP, and 4E-BP1)." (PMID 37794467, 2023).
type 2 diabetes (1 paper, 2025). "A final group of five biomarkers (CXCL9, IL-2RB, MMP-10, STAMBP, TNF-α) showed positive associations with changes in CES-D in people with type 2 diabetes but without significant effect modification (pinteraction ≤ 0.18)." (PMID 40624224, 2025).
tumor (9 papers, 2021 to 2025). "Similar to the protumor effect of RAI14 in vitro, the overexpression of RAI14 reversed the xenograft tumor reduction caused by the knockdown of STAMBP to a certain extent." (PMID 36434041, 2022). "The STAMBP level was closely associated with tumor size, lymph node invasion and neoplasm disease stage." (PMID 34102455, 2021). "The results showed that STAMBP expression was associated with tumor size, lymph node invasion and neoplasm disease stage in the LUAD patients." (PMID 34102455, 2021). "Our findings further demonstrate the anti-tumor efficacy of the STAMBP inhibitor entrectinib in BRCA cells, underscoring its promise as a therapeutic candidate for future development." (PMID 41301420, 2025). "The STAMBP-knockdown group showed reduced xenograft tumor growth, which was accompanied by a reduction in tumor volume and tumor weight." (PMID 36434041, 2022). "To study the effect of the STAMBP-RAI14 pathway on tumor growth in vivo, we injected control or STAMBP-knockdown MDA-MB-231 cells stably expressing HA-RAI14 into the axillary area of BALB/c nude mice to establish a xenograft model." (PMID 36434041, 2022). "We also evaluated the STAMBP mRNA level in normal lung and tumor tissues of NSCLC patients using TCGA database." (PMID 34102455, 2021). "In contrast, STAMBP expression in the nuclei of tumor cells was downregulated in 51 patients (68%), unchanged in 12 patients (16.0%) and upregulated in 12 patients (16.0%) out of 75 patients compared with the corresponding noncancerous epithelial cells." (PMID 34102455, 2021). "The results showed that STAMBP, EGFR, phosphorylated EGFR and ERK were markedly reduced, whereas the ERK levels remained unchanged in the STAMBP knockdown tumor tissues." (PMID 34102455, 2021). "To assess the effect of STAMBP on tumor growth and metastasis in vivo, we established A549 cells with stable STAMBP knockdown by lentivirus-mediated shRNA expression." (PMID 34102455, 2021). "STAMBP expression is elevated in the cytoplasm of tumor cells and reflects the severity of the disease." (PMID 34102455, 2021). "STAMBP staining was markedly increased in the cytoplasm of the tumor cells compared with that of the lung epithelial cells from noncancerous tissues." (PMID 34102455, 2021). "Our findings describe a unique pathway of EGFR regulation and identify STAMBP as a potential therapeutic target to suppress LUAD tumor metastasis." (PMID 34102455, 2021). "STAMBP promotes cell migration and invasion in vitro, and STAMBP knockdown suppresses tumor growth and metastasis in a xenograft mouse model." (PMID 34102455, 2021). "Stronger STAMBP staining was observed in the cytoplasm of the tumor cells from 32 out of 75 patients (42.7%)." (PMID 34102455, 2021). "STAMBP expression is elevated in the cytoplasm of tumor cells, which provides further support for its roles in regulating EGFR stability and promoting EGFR recycling to the membrane." (PMID 34102455, 2021). "In contrast, strong STAMBP staining was detected in the cytoplasm, and weak staining was detected in the nucleus of the tumor cells." (PMID 34102455, 2021). "Both in vitro cellular assays and in vivo subcutaneous tumor models demonstrated that combining STAMBP inhibition with tamoxifen significantly enhanced therapeutic efficacy, confirming our hypothesis." (PMID 41301420, 2025). "Dysregulated STAMBP expression induces oncogenic features through altered ubiquitin signaling of substrate proteins by directly binding with the C-terminal JAMM domain of STAMBP, which could facilitate cellular transformation and tumor development." (PMID 41301420, 2025). "We found that the suppression of STAMBP expression could also restore the therapeutic effects of tamoxifen in the xenograft tumor model (p < 0.05)." (PMID 41301420, 2025). "Our study attempts to seek to address how STAMBP regulates ER-positive tumor progression and whether STAMBP inhibition can resensitize endocrine-resistant cells to tamoxifen." (PMID 41301420, 2025).